KIR3DL2 (killer cell immunoglobulin like receptor, three Ig domains and long cytoplasmic tail 2)
Diseases named in the same sentence as KIR3DL2 in open-access papers (continued):
Sharing a sentence is not in itself a finding about the gene and the disease.
tumor (continued). "Finally, IF labeling allowed validation of tumor T cells’ clearance with the disappearance of infiltrating KIR3DL2+ T cells." (PMID 36230895, 2022). "In addition, immunostaining analysis allowing detection of human CD3 and KIR3DL2 tumor marker confirmed the presence of double positive cells in the dermis." (PMID 36230895, 2022). "AZU1 and KIR3DL2 were potentially related with tumor immune microenvironment." (PMID 32732980, 2020). "KIR3DL2 inhibits natural killer–mediated lysis after interaction with HLA-A, may prevent elimination of tumor cells." (PMID 31139323, 2019). "Recently it has been shown that in primary anaplastic large-cell lymphoma, an aggressive CD30+ CTCL, tumor cells also express KIR3DL2 and can be the target of a potent anti-tumor activity in vitro, re-enforcing this marker as a therapeutic target for these patients." (PMID 28912774, 2017). "KIR3DL2's role in the regulation of the immune response is intriguing in light of the tissue specific expression, and perhaps the identification of this gene using our method is an indication of the extent of the involvement of immune cells in tumor samples." (PMID 27536319, 2016). "Furthermore, in the Sézary Syndrome, in which KIR3DL2 represents a specific marker for the assessment of circulating tumor burden and for patient follow-up, CpG-ODN has been shown to promote not only the internalization of KIR3DL2 receptor but also the generation of apoptotic signals." (PMID 31316503, 2019). "KIR3DL2 detection permits to estimate whether the ongoing treatment specifically targeted the malignant T-cell clone and, if so, to visualize the pool of residual tumor cells." (PMID 28912774, 2017). "The gene signatures of the TCM group include TOX, KIR3DL2 and GTSF1, which were previously reported in tumor-stage MF and Sézary syndrome." (PMID 35241665, 2022). "Thus, CpG-ODN may exert a direct anti-tumor effect on Sézary cells through binding to KIR3DL2." (PMID 31316503, 2019). "IPH-4102 is a humanized IgG1 antibody against KIR3DL2 whose potent antitumor properties ex vivo against SS and CTCL primary cells, and in vivo against KIR3DL2-positive tumor cells are achieved mainly through ADCC and ADCP." (PMID 29387053, 2017). "The limited expression of KIR3DL2 on normal immune cells, in comparison with the ectopic expression on CTCL tumor cells, allows to selectively and efficiently kill malignant cells." (PMID 28912774, 2017). "KIR3DL2 mAb identifies the tumor cells in most CTCL patients analyzed and, therefore, represents a valid tool to dynamically evaluate the evolution of the tumor pool during disease evolution as well as the response to treatment." (PMID 28912774, 2017). "Patients exhibiting lower KIR3DL2 expression levels displayed poorer prognosis, as evidenced by reduced overall survival (OS), recurrence-free survival (RFS), progression-free survival (PFS), and disease-specific survival (DSS) rates, indicating a higher tendency for tumor recurrence and mortality." (PMID 39262781, 2024). "KIR3DL2 expression is not restricted to SS and MF tumor cells." (PMID 28912774, 2017). "Importantly, we found a population of IGFL2+ KIR3DL2+ tumor cells that was largely absent in nonlesional MF or healthy control skin, which might be crucially involved in the formation of actively inflamed, clinically visible MF lesions." (PMID 34583709, 2021).
cancer (12 papers, 2011 to 2025). A tumor composed of atypical neoplastic, often pleomorphic cells that invade other tissues. "Using our optimal soft threshold for each cancer, the empirical p-values testing for differences in coexpression at KIR3DL2 were 0.02 for OV, 0.03 for BRCA, 0.002 for LUAD, and 0.05 for SKCM." (PMID 27536319, 2016). "After comparing these sets of genes across the four cancers, one gene (KIR3DL2) consistently showed differential coexpression patterns between the null and missense groups." (PMID 27536319, 2016). "After repeating a similar selection of genes for all four cancers, we examined the overlap among the selected gene lists across the four cancers, and identified 164 genes that were differentially correlated to KIR3DL2 in all four cancer types." (PMID 27536319, 2016). "Only one gene, KIR3DL2, displayed prominent differential coexpression across all cancers and soft thresholds." (PMID 27536319, 2016). "The marginal expression levels of KIR3DL2 vary from one cancer type to another." (PMID 27536319, 2016). "Furthermore, it is interesting to note that upregulation of genes, such as ANKRD22, FRMD6, and KIR3DL2, and down-regulation of genes, such as TIMP3, SAP25, NAPSA, and TIMP are associated with a worse prognosis in cancer, are also associated with a worse prognosis in AdHF." (PMID 29236770, 2017). "Further, the first-in-class anti-KIR3DL2/CD158k humanized NK-mediated ADCC-inducing antibody lacutamab (IPH4102), designed to selectively destroy CTCL cancer cells, presents a compelling option." (PMID 38272918, 2024). "For our fourth cancer, SKCM, KIR3DL2 showed significant evidence (nominal p < 0.05) for differential coexpression with 3 of the 4 soft thresholds analyzed, and was non-significant at the threshold of 0.05 (nominal p = 0.069) for the fourth soft threshold." (PMID 27536319, 2016).
infection (4 papers, 2009 to 2021). The state of being infected such as from the introduction of a foreign agent such as serum, vaccine, antigenic substance or organism. "Given that KIR3DL2+NKL cells prefer exogenous ssDNA over dsDNA, we also compiled genomic datasets consisting only of viruses that use ssDNA during infection or as their primary genetic material (ssDNA-vectors)." (PMID 34760351, 2021).
bacterial infection (1 paper, 2012). "Since both disorders are associated with bacterial infection, it is possible that bacterial exposure in general may have a role in promoting the expansion of KIR3DL2-expressing T cells." (PMID 23162554, 2012).
infectious disease (1 paper, 2019). A disorder directly resulting from the presence and activity of a microbial, viral, or parasitic agent in humans. "In addition, KIR3DL2 is considered to have a low inhibitory ability and the interaction with its ligand HLA-A3 and HLA-A11 is extremely peptide-specific present in the groove, which allows the epitopes A3 and A11 to present peptides from different infectious diseases." (PMID 31525196, 2019).
neurodegenerative disease (1 paper, 2021). A disorder of the central nervous system characterized by gradual and progressive loss of neural tissue and neurologic function. "In addition, differentially expressed genes in B cells were identified; both the upregulated genes (KIR3DL2, QPCT, PPP2R2B) and the downregulated genes (FRAT2, WWC3, SPG20) had certain connections with neurodegenerative diseases." (PMID 34880454, 2021). "In B cells, the upregulated genes KIR3DL2, QPCT, and PPP2R2B are all involved in neural function and neurodegenerative diseases, and the downregulated genes FRAT2 and WWC3 are involved in the Wnt/β-Catenin signaling pathway, which is associated with AD pathogenesis." (PMID 34880454, 2021).
KIR3DL2 also shares sentences with these, for which no sentence is quoted: viral infections (8 papers); lupus (5); Autoimmunity (3); rheumatoid arthritis (3); acute myelogenous leukemia (2); autism (2); hepatitis B (2); hepatocellular carcinoma (2); ischemic stroke (2); melanoma (2); Multiple Myeloma (2); myelodysplastic syndrome (2); acute graft versus host disease (1); acute kidney injury (1); AIDS (1); allergic disease (1); anaplastic large cell lymphoma (1); Ascites (1); Atrophy (1); B cell lymphoma (1); Behcet syndrome (1); brain trauma (1); breast carcinoma (1); Chagas disease (1); classic Hodgkin lymphoma (1); Crohn disease (1); diffuse large B-cell lymphoma (1); endometriosis (1); gastric cancer (1); gastrointestinal stromal tumor (1).
A further 23 diseases each share a sentence with KIR3DL2 in 1 paper.